FOXA1 (forkhead box A1)
Diseases named in the same sentence as FOXA1 in open-access papers (continued):
Sharing a sentence is not in itself a finding about the gene and the disease.
tumor (continued). "Given the putative growth-regulatory role of Foxa1 in mouse C cell precursor subsets, its differential expression in MTC predicted that cancer cell proliferation might be patterned in a similar manner depending on the tumor context." (PMID 26395490, 2015). "When visualized using RNA in situ hybridization, this transcript showed elevated expression in early neoplasia and cancer compared with normal, with staining patterns correlating well with the elevated staining of ER, FOXA1, and GATA3 in the majority of neoplasia cases (data not shown)." (PMID 24887547, 2014). "The effects of FOXA1 depletion and FOXA1 overexpression on AR-mediated transcription as well as Notch pathway and their impact on EC cell proliferation were examined by qRT-PCR, western blotting, co-immunoprecipitation, ChIP-PCR, MTT, colony-formation, and xenograft tumor–formation assays." (PMID 24512546, 2014). "However, while FOXA1 silencing resulted in increased in vivo tumor proliferation, this did not appear to result in increased invasion in our tissue recombination experiments." (PMID 22590586, 2012). "The absence of FOXA1 in luminal/ER-positive breast cancer patients may contribute to identify the 30% of ER-positive tumours that are not hormone responsive." (PMID 19549328, 2009). "Moreover, the multivariate analysis, including the tumour size and lymph node status, demonstrated the independent value of FOXA1 as a predictor of patient outcome in ERα-negative tumours." (PMID 19549328, 2009). "Additionally, the multivariate Cox hazard analysis, with models including tumour size and lymph vascular invasion, demonstrates the independent value of FOXA1 expression as a predictor of patient outcome in ERα-negative tumours." (PMID 19549328, 2009). "Recent studies have found that PCa cells that express high levels of FOXA1 are capable of driving tumor cell growth, even in the presence of reduced or absent androgen levels, suggesting that tumors with higher levels of FOXA1 may have a growth advantage after androgen deprivation." (PMID 38605023, 2024). "Therefore, to identify whether FOXA1 and HOXB13 are colocalized with AR in the regulatory regions (−5 kb/+2 kb from TSS) of the DE-lncRNAs, we used previously published FOXA1 and HOXB13 ChIP-seq data in PCa tumor samples." (PMID 37140987, 2023). "Interestingly, the fact that FOXA1 does not follow a strong sample‐specific pattern similar to AR binding suggests that there is an AR‐independent function of FOXA1 in these metastases samples, in line with recent evidence in primary tumor development." (PMID 33576154, 2021). "However, knockdown of FOXA1 resulted in a significant reduction of cellular viability on day 5, suggesting that FOXA1 has essential roles for viability of the ER-positive tumor cell lines, although there were no direct effects on ER and AR activities." (PMID 29137314, 2017). "The findings show that FOXA1 cobinds with HNF4G in the classical subtype of PDAC, but that FOXA1 is not a PF in this PDAC subtype and, instead, the key transcription factor driving primary tumor growth appears to be HNF4G." (PMID 41168397, 2025). "Similar to FOXA1, overexpression of HOXB13 in an non-neoplastic prostate cell line pushed the AR cistrome to a more tumor-like profile." (PMID 40833121, 2025). "Similarly, further studies are needed to determine the frequency of ER+ tumors that are negative for both PR and CAXII (one tumor in our cohort, positive for FOXA1 and GATA3), and whether these tumors are also negative for other ER target genes and are unresponsive to hormonal therapies." (PMID 36358871, 2022). "FOXA1, STK11, TSC1 and TSC2 were found to have no concordance between tumours and were largely restricted to metastases." (PMID 32811538, 2020). "Tumor samples with absent immunoexpression of GATA3, FOXA1 and CK5/6 showed significantly lower transcript levels of GATA3, FOXA1 and KRT5/KRT6A, respectively (p < 0.001, p = 0.0130, p < 0.0001 and p = 0.0278)." (PMID 32758253, 2020).
tumor (continued). "In the absence of FoxA1/2 activity, NKX2-1-negative tumor cells adopt a more proximal cell fate with features of either the transitional epithelium of the SCJ or the squamous epithelium of the forestomach/esophagus, depending on the context of FoxA1/2 loss." (PMID 30475207, 2018). "The second half showed significantly higher mRNA expression levels of the Uro‐diff gene signature, as well as of the key transcription factors FOXA1 and GATA3, and appeared to be indistinguishable from GU cases at the tumour‐cell level." (PMID 28195647, 2017). "The presence of FoxA1+/ER+/PR+ LOP cells in the 129:Stat1−/− mammary ducts and neoplasms is also consistent with a ductal, rather than alveolar, origin of the tumors." (PMID 28865492, 2017). "On the contrary, tumours with significantly increased TUG1 expression, which encompass 8% of TCGA cases, were usually positive for markers of a luminal subtype, e.g. FOXA1, GATA3, but not for basal KRTs." (PMID 28430799, 2017). "One portion of the SCCL/Mes‐Inf cluster was negative for KRT5/KRT14 and FOXA1/GATA3, as well as for CDH3 expression, making it distinct from basal/SCC‐like tumours." (PMID 28195647, 2017). "As expected, HPAF-II xenografts showed glandular structures, typical of highly differentiated tumors, with higher FOXA1 expression, whereas PANC-1 xenografts exhibited solid and compact tumor sheets without lumens, indicative of poor differentiation, along with higher GATA2 and ABCC4 expression." (PMID 39114357, 2024). "It is unclear whether the enriched binding sites for FOXA1, HOXB13 and CDX2 are dependent or independent of AR activity in single cells from high-grade tumours." (PMID 34911933, 2021). "Interestingly, we observed an enrichment for FOXA1 and HOXB13 in Gleason pattern 4 tumours independent of their ERG accessibility." (PMID 34911933, 2021). "The evaluation and interpretation of immunohistochemical AR and FOXA1 expression were not standardized and the use of TMA tumor blocks with small sized cores may not have been able to represent the results of whole sections." (PMID 29137314, 2017). "However, these two basal/SCC‐like tumour categories do not differ in their KRT5, KRT14/FOXA1, GATA3 ratios, their defining characteristics, or their shifts to high CDH3 and lower CDH1 expression." (PMID 28195647, 2017). "To this end, we isolated cells derived from non-depleted (Dox−) FoxA1 or FoxA2 MCF7 and MDA231 tumours (control groups, GFP+/tRFP−), FoxA1- and FoxA2-depleted MCF7 and MDA231 tumours (GFP+/tRFP+), and the corresponding FoxA family-rescued tumours (GFP+/tRFP+), respectively." (PMID 27045898, 2016). "Since SSTR1 is downregulated after ARSI, we examined the reciprocal relationship between the AR/FOXA1/HOXB13 transcription machinery and SSTR1 expression, specifically the effect of testosterone (as opposed to ADT and ARSIs) on SSTR1 expression and tumor growth." (PMID 39352383, 2024). "In addition, FOXA1 and MSX2 were up-regulated in tumor samples compared to normal samples in TNBC patients and were experimentally validated to induce the EMT process and tumor metastasis." (PMID 36291687, 2022).
cancer (333 papers, 2009 to 2026). A tumor composed of atypical neoplastic, often pleomorphic cells that invade other tissues. "These deletions are located within the mutational hotspot across cancers that modify the transcriptional activity of FOXA1." (PMID 41009328, 2025). "We created a FOXA1 reporter construct and designed inhibitors targeting key molecular pathways commonly implicated in cancer cell proliferation, survival, and apoptosis." (PMID 41395253, 2025). "Together, these germline risk variants would dysregulate the FOXA1/AR equilibrium via remodeling promoter accessibility, potentially converting LE-2 cells into a cancer-prone state." (PMID 41468516, 2025). "Our PLA analysis detected a marked endogenous association between REV-ERBα and FOXA1 in the different cancer cells." (PMID 39383000, 2024). "Gene set enrichment analysis (GSEA) showed that FOXA1 knockout resulted in the enrichment of cancer hallmark signatures including E2F targets, MYC targets and NOTCH signaling, and other molecular events including cell cycle, DNA replication and keratinization." (PMID 39687207, 2024). "Genes shared by cluster A and D represent a link between chromatin organization and cancer hallmark processes, involving FOXA1, ESRI, PHF14 and the ATPase proteasome subunits, PSMC5 and PSMC4." (PMID 38625038, 2024). "Nuclear FGFR1 has been shown to interact with the CBP/CREB complex, Nurr1, RNA polymerase II or FOXA1 and has so far been mainly associated with the regulation of gene expression in healthy and cancer cells." (PMID 37480072, 2023). "Mechanistically, SMARCD3 acts with FOXA1 to control lipid and fatty acid metabolism, programs associated with therapy resistance and poor prognosis in cancer." (PMID 36653361, 2023). "In our research, we investigated the potential role of the FOXA1, a transcription factor, in pan-cancer and EOC and its underlying molecular mechanism on promoting EMT." (PMID 36393971, 2022). "High FOXA1 expression was mainly associated with extracellular matrix organization, cancer, and mitosis." (PMID 35968505, 2022). "HOXB13, like FOXA1, is a pioneer transcription factor involved in establishing a cancer-associated AR cistrome." (PMID 36212399, 2022). "IGF2, a prosurvival factor which is usually employed by cancer cells in response to different stressful stimuli, was repressed by loss of FOXA1 but upregulated by gain of FOXA1." (PMID 35974000, 2022). "The transcription factor FOXA1, the activity of which is associated with embryonic and postembryonic development, as well as with various cancers, can act as an activator of L1 expression." (PMID 34680956, 2021). "Low forkhead box A1 (FOXA1) protein expression significantly correlates with high-grade carcinoma, loss of estrogen receptor α (ERα) and PR, and poor survival." (PMID 34804263, 2021). "A model has been proposed in which a promoter mutation causes enhanced expression of FOXA1, this way promoting accessibility of oestrogen receptor binding sites, which allows cancer cells to grow under lower oestrogen conditions." (PMID 32847043, 2020). "Several studies have found that FOXA1 expression in cancer tissues was associated with multiple types of human cancers, reflecting its crucial roles in cellular processes." (PMID 32207560, 2020). "FOXA1 plays a regulatory role in the evolution and development of organisms, and the recent studies revealed that FOXA1 is associated with a variety of cancers, such as prostate, breast, and gastric." (PMID 32812032, 2020). "With the cancer cells, CHiP analysis indicated that the level of FOXA1 associating with the IGFBP2 gene was minimal in comparison to the normal cells." (PMID 32655839, 2020).
cancer (continued). "AR overexpression (found in 33 cases/180, 18%) and FOXA1 index ≥1% (64/180, 36%) were associated with a longer disease-free interval, overall survival, and cancer-specific survival in cats with FMC." (PMID 31888566, 2019). "Along with SPOP-mutant cancers, FOXA1-mutant cancers have been associated with the highest levels of AR transcriptional activity." (PMID 29581876, 2018). "Function gain and loss analysis was performed to determine the role of FOXA1 in cancer cells derived from male HCC patients." (PMID 29208003, 2017). "Our results also raise the possibility that other semaphorins or their receptors fall under AR, GATA2, or FOXA1 regulation, especially given that many semaphorin family members are implicated in cancer." (PMID 28038451, 2017). "The cancer risk allele (C) triggers stronger FoxA1 and PolII binding, enhanced transcription activity, and increased FGFR2 expression level." (PMID 27825120, 2016). "Another study showed that rs4784227 are enriched in the cistromes of FOXA1 and ESR1 in a cancer-cell specific manner, modulating the affinity of chromatin for FOXA1 and resulting in allele-specific gene expression." (PMID 25531440, 2014). "Here, we describe, for the first time, the association between FOXA1 expression and the Notch pathway in cancer." (PMID 24512546, 2014). "In this study, the silencing of FOXA1 causes a partial shift from luminal to basal gene expression signatures, which results in an increased migration and invasion of luminal cancer cells." (PMID 23192763, 2013). "Foxa1 has been shown to facilitate chromatin access to Smad transcription factors, mediators of Tgf-β signaling, a pathway implicated in cancer and also enriched in Foxa1-only elements." (PMID 22737085, 2012). "In this study, we present genetically engineered mice with targeted knock-in of human cancer-associated FOXA1 mutant transgenes, which provide crucial mechanistic insights into the divergent mechanisms of FOXA1 Class 1 and Class 2 alterations in PCa formation and progression." (PMID 40570057, 2025). "Importantly, we identify cancer-associated FOXA1 indels affecting residue F254 as loss-of-function mutations promoting dedifferentiation of adult prostate progenitors." (PMID 39633177, 2025). "In various cancer types, FOXA1 has been implicated as an oncogene." (PMID 40623983, 2025). "FOXA1 loss-of-function mutations could represent a genetic vulnerability in a subset of cancer patients." (PMID 39633177, 2025). "Cancer-associated fibroblasts (CAFs) and normal fibroblasts (NFs) were isolated from cancerous tissues and matched with paracancerous tissues to study the role of the interaction between miR-93-5p, forkhead box A1 (FOXA1), and TGFB3 in radioresistance in CRC." (PMID 37237523, 2023). "FOXA1 is associated with malignant tumors, but the function of FOXA1 in EOC is unclear." (PMID 34991620, 2022). "We propose, therefore, that the deregulated expression of FOXA1 in cancer cells might affect the primary cilium, causing eventually aberrant hedgehog signalling." (PMID 36509813, 2022). "In cancer, mutations including SNVs and structural variants (SVs) can alter the activity and interactions between CREs to drive aberrant gene expression, which is seen in the case of FOXA1." (PMID 32946061, 2021). "FOXA1 has also been implicated in the regulation of NOTCH1 in other cancer types." (PMID 34831307, 2021). "However, we observed two cancer samples with both SPOP or FOXA1 mutations and fusion of an ETS transcription factor." (PMID 31537872, 2019). "FOXA1 positivity (index ≥1%) was also associated with favorable outcome in luminal FMCs, in terms of disease-free interval (HR = 0.39, 95% CI: 0.21–0.75; p = 0.002) and cancer-specific survival (HR = 0.46, 95%-CI: 0.24–0.87; p = 0.014)." (PMID 31888566, 2019). "High expression of FOXA1 in cancers is usually associated with favorable clinical outcome." (PMID 29864144, 2018).
cancer (continued). "In our samples, 1.53% of cases had deletions in FOXA1, which may potentially reduce the risk of cancer, leading to a healthier lifespan." (PMID 29883365, 2018). "High methylation levels of this gene may cause low expression levels, which in combination with FOXA1’s functions of regulating the cell cycle and apoptosis, can lead to cancer." (PMID 29983747, 2018). "These CNV regions encode nineteen known genes, and some of which have been shown to affect aging-related phenotypes such as the shortening of telomere length (ZNF208), the risk of cancer (FOXA1, LAMA5, ZNF716), and vascular and immune-related diseases (ARHGEF10, TOR2A, SH2D3C)." (PMID 29883365, 2018). "Enrichment of known pathways/genes associated with HR positivity was observed, including ER signaling, strong FOXA1 and TGFβ expression, and enrichment of gene expression associated with the antigen-presenting machinery, consistent with the generally immune-cold features of luminal cancers." (PMID 41123599, 2025). "Finally, we performed a targeted sequencing study that included mutated genes found in whole-genome/exome sequencing studies, genes frequently mutated in all cancers, and FOXA1 and the 0–200 kb upstream region in all 48 patients with EMPD and 14 patients with MPD." (PMID 32235312, 2020). "Thus, it remains to be determined whether RING1B functionally associates with FOXA1 and AR in other cancer types or during embryonic development." (PMID 30139998, 2018). "The results identify a new molecular link between cell cycle regulators and regulation of differentiation genes (such as GATA3 and FoxA1) that offers insights also into how over-expression of FoxM1 might be playing a causal role in maintaining poorly differentiated state of cancer cells." (PMID 28387346, 2017). "The axis had been demonstrated to be involved in many kinds of cancer-related processes, like facilitating cancer cell growth and modulating cell cycle through TGFβ1 or β-catenin pathways, respectively, and participating in cellular growth and proliferation associated with FOXA1/2." (PMID 27167111, 2016). "SMARCD3 cooperates with FOXA1 to control lipid and fatty acid metabolism, resulting in therapy resistance and poor prognosis in cancer." (PMID 40454484, 2025). "Using the Caris Life Sciences POA database, we examined the alterations of FOXA1 in 20 cancer types encompassing 191,586 solid tumors." (PMID 39745364, 2025). "To better understand the role of FOXA1 in resistance to doxorubicin, we inhibited its expression using siRNA or its miRNA-212-3p inhibitor then studied the effect on the cancer cell lines survival using SRB assay." (PMID 40216647, 2025). "In total, 41 and 65 differentially enriched genes were identified from CUT&Tag and ChIP-seq data, respectively, with only FOXA1 and IER2 appearing in both datasets, highlighting FOXA1 as a conserved, cancer-specific SE target." (PMID 41330917, 2025). "Among the key players driving these aggressive phenotypes, the transcription factor forkhead box A1 (FOXA1) has been identified as a critical regulator of AR reprogramming, enabling oncogenic transcriptional programs during cancer progression." (PMID 41395253, 2025). "Our study paves the way for pharmacological strategies aimed to restore near-physiological FOXA1 activity in cancer cells." (PMID 39633177, 2025). "The activities of SREBF1 and FOXA1 were higher in the primary cancer samples, while the activities of FOXC1 and TP73 were higher in normal samples, and the activities of transcription factors such as FOXA3 were higher in the CRPC samples." (PMID 39988626, 2025). "In the context of NPC, a highly malignant cancer often diagnosed at advanced stages, FOXA1 appears to play a protective role." (PMID 40623983, 2025). "As FOXA1 plays a vital role in EMT progression in many cancers, such as breast and liver, we decided to investigate the expression levels of some FOXA1 downstream EMT genes." (PMID 40216647, 2025).